SIRT1 (sirtuin 1)
Diseases named in the same sentence as SIRT1 in open-access papers (continued):
Sharing a sentence is not in itself a finding about the gene and the disease.
cancer (continued). "Moreover, SIRT1 activities seem to coordinate cancer stem cell-EMT changeover through deacetylation of a complex circuitry of transcription factors." (PMID 30319540, 2018). "SIRT1 deacetylates β-catenin and promotes the proliferation of cells in various cancers." (PMID 30115982, 2018). "Targeting epigenetic enzymes to prevent EMT is an appealing approach to limit cancer dissemination, but inhibiting SIRT1 activity alone might have limited effect and will require drug combination to efficiently prevent EMT." (PMID 30445998, 2018). "In fact, bifurcated SIRT1 can act as either a tumor suppressor or promoter in cancer cells." (PMID 30380732, 2018). "However, a dual function of SIRT1 in tumor promotion and suppression has been described in different cancer types." (PMID 30217020, 2018). "Simultaneously, the role of SIRT1 in cancer progression has been studied, however, whether SIRT1 acts as a tumor suppressor or tumor progressor has not been elucidated yet." (PMID 29996516, 2018). "We might assume that elevated Sirt7 levels inhibit Sirt1-mediated heterochromatin formation at pericentric regions thereby contributing to global genomic instability in cancer cells." (PMID 29963979, 2018). "However, despite obvious epigenetic capabilities, HDACs and SIRT1 current relevance for cancer strive on their now known ability to act on different substrates." (PMID 30319540, 2018). "Other specific sirtuin inhibitors (SIRTi) have been reported to trigger cancer cell death, including the SIRT1 inhibitors NCO-01 and -04, and the SIRT2 inhibitors AEM1 and AEM2, which induce cell death in T-cell leukemia/lymphoma and in non-small cell lung cancer, respectively." (PMID 29401749, 2018). "SIRT1, 2, and 3 levels were downregulated shown to be in the Ishikawa cancer cells following a high dose (5 μM) MHY2256 or salermide (50 μM) treatment, suggesting that MHY2256 might target various SIRT proteins." (PMID 30217020, 2018). "Previous studies in several types of cancers also showed SIRT1 overexpression was correlated with advanced stages or poor prognosis and inhibition of SIRT1 may suppress tumor progression." (PMID 29636061, 2018). "Although many researchers have shown that SIRT1 promotes metastasis in various cancers, certain studies have still shown that SIRT1 may serve as a suppressor gene for tumor metastasis." (PMID 29374154, 2018). "Moreover, CPEB1 appears to regulate the polyadenylation and translation of SIRT1 to mediate cancer stemness in vitro and in vivo." (PMID 30237545, 2018). "However, the mechanism by which SIRT1 inhibitors, such as nicotinamide, sensitize cancers to therapy has largely been attributed to SIRT1’s role in DNA damage repair." (PMID 29717261, 2018). "Among the predicted targets of miR-29b such as signal transducer and activator of transcription 3 (Stat3), cyclin-dependent kinase 6 (CDK6), lysine demethylase 2A (KDM2A) and Sirtuin-1 (SIRT-1), SIRT-1 was reported to be associated with chemoresistance in cancers." (PMID 29552311, 2018). "Additionally, MK-1775 has promising synergistic antitumor effect when combined with CHK1 inhibitors LY2603618 and Sirt1 inhibitor Ex527 in various malignancies, suggesting a novel strategy for MK-1775-mediated cancer treatment." (PMID 30323762, 2018). "SIRT1 has been shown to promote survival as a defensive mechanism to prevent stress-induced cell death in myoblasts, and is involved in several processes including: cardiovascular disease, neurodegeneration, inflammation, cancer, and regulation of metabolism." (PMID 29487709, 2018). "Specifically, in cancer cells, the role of Sirt1 is controversial." (PMID 30304806, 2018). "Various preclinical studies demonstrate SIRT1 as an effective anti-cancer target." (PMID 29520231, 2018). "However, the role of SIRT1 in cancer progression has been controversial, with some studies reporting a tumorigenesis function and others reporting a tumor-suppressor function." (PMID 30237545, 2018).
cancer (continued). "On the premise that SIRT1 is upregulated in various human cancers, SIRT1 could act as a tumor promoter." (PMID 30380732, 2018). "Accumulating evidence has recently revealed that SIRT1 may act as a tumor suppressor in several types of cancer, and thus activating SIRT1 would represent a possible therapeutic strategy." (PMID 29991742, 2018). "SIRT1 is involved in key cellular processes such as apoptosis, DNA repair, chromatin remodeling and cancer development, but its role in carcinogenesis is controversial, as it can have both tumor-suppressive and tumor-promoting functions, mainly depending on cancer type." (PMID 29340027, 2017). "Furthermore, increase of SIRT1 has been reported to promote the tumorigenesis, cancer cell growth, metastasis and resistance to chemotherapeutic agents." (PMID 29228612, 2017). "A number of preclinical studies have suggested that blocking SIRT1 activity might be a promising strategy for various cancers of the digestive system." (PMID 28977971, 2017). "Oligonol, an antioxidant polyphenolic compound showing anti-inflammatory and anti-cancer properties, mainly found in lychee fruit, may act as an anti-ageing molecule by modulating the SIRT1/autophagy/AMPK pathway." (PMID 28258519, 2017). "The deregulation of SIRT1 expression has been found in various cancers." (PMID 28977971, 2017). "Nowadays, many studies demonstrated that aberrant expression of SIRT1 was found in various cancers, containing hepatocellular carcinoma, gastric carcinoma, breast carcinoma and colorectal carcinoma, indicating that SIRT1plays important roles in the initial and progress of cancers." (PMID 28977967, 2017). "The dual nature of Sirt1 in cancer remains a controversy and could be a consequence of several factors including its different expression levels in various types of carcinoma, its subcellular location, and diverse downstream substrates." (PMID 29029516, 2017). "Resveratrol, SIRT1 activator, inhibits carcinogenesis predominantly performed in transgenic animal models, orthotopic cancers of nude mice or different cancer cell lines, but its effects during process of spontaneous tumors using vertebrate models remain untested." (PMID 28903430, 2017). "Sirt1, because of its tumorigenic characteristics, can be targeted for therapy, which may provide a longer lifespan and better quality of life for cancer patients." (PMID 29029516, 2017). "The overlap of changed genes between the cell lines was small, but the involved pathways in the reactome and GO- analyses showed a high overlap with DNA methylation, cell cycle, SIRT1, PKN1 pathway, DNA repair and oxidative stress as well known cancer-associated representatives." (PMID 29348853, 2017). "Consequently, the clinical significance of SIRT1 in cancers is complex and requires further investigation." (PMID 29029516, 2017). "It has been proposed that subcellular localization may account for the dual roles of SIRT1 in normal versus cancer cells." (PMID 29029516, 2017). "In view of its role in cancer metabolism, SIRT1 tends to be a tumor promoter." (PMID 27659520, 2017). "Potential sources of heterogeneity, including cancer type, geographic area, SIRT1 expression level, primary antibody used for the immunohistochemical evaluation of SIRT1 expression, method of data extraction, confounding adjustment, and quality score, were assessed with meta-regression analysis." (PMID 28977971, 2017).
cancer (continued). "Although an overwhelming number of studies have established evidence that indicates an unfavorable impact of Sirt1 overexpression on patient prognosis in a wide range of carcinomas, several recent investigations revealed a superior survival duration in cases with abnormal expressions of Sirt1." (PMID 29029516, 2017). "Sirt1 promotes tumorigenesis by boosting cell survival under stress conditions but facilitates uncontrolled cell proliferation, and additionally, it can defend against carcinomas by increasing genomic stability and limiting cellular replicative lifespan." (PMID 29029516, 2017). "In conclusion, SIRT1 plays differential roles in cancer and stromal cells." (PMID 26992208, 2016). "In this regard, the activation of SIRT1 in FOXM1 overexpressed tumors may prove to be a potential weapon in fighting these types of cancers." (PMID 27542221, 2016). "Additionally, overexpression of SIRT1 in tumour cells is correlated with silenced tumour suppressor genes, cancer resistance to chemotherapy and ionising radiation." (PMID 27793039, 2016). "Therefore, we here designed an in vivo tumor model using SIRT1-transgenic mice and a co-culture model of cancer and stromal cells." (PMID 26992208, 2016). "Our findings suggest that the reduced SIRT1 expression by tNOX knockdown was found to reduce various cancer phenotypes, and this phenomenon is similar to the way in which sphingosine kinase 1 (Sphk1) and S1P upregulate SIRT1 expression to enhance cell proliferation and migration." (PMID 27367652, 2016). "Inhibiting FOXM1 acetylation or increasing its deacetylation activity by the activation of SIRT1 may provide an efficient strategy to fight FOXM1 overexpressed cancers." (PMID 27542221, 2016). "Our main concern is why there are conflicting reports regarding the role of SIRT1 in cancer." (PMID 26992208, 2016). "Next, we investigated whether the SIRT1-dependent paracrine factor from fibroblasts affects proliferation in other cancer cell-lines." (PMID 26992208, 2016). "In addition, the growth of these cancer cells was inhibited in co-culture with MEF-1 or CCD18Lu fibroblasts where SIRT1 was knocked down." (PMID 26992208, 2016). "The correlation between SIRT1 expression and malignant tumours has been reported previously." (PMID 27793039, 2016). "SIRT1 expression was evaluated separately in stromal fibroblasts and cancer cells." (PMID 26992208, 2016). "In addition, SIRT1 deacetylates and inactivates NF-κB, which plays a beneficial role in cancer survival under stressful conditions like inflammation, and HIF-1α, which promotes cancer survival under hypoxic microenvironment." (PMID 26992208, 2016). "Fibroblasts may release some cancer-proliferating factor(s) SIRT1-dependently, but SIRT1 may provoke an intracellular event to inhibit cancer growth." (PMID 26992208, 2016). "Taken together, SIRT1 may participate in tumour formation and progression in many different kinds of cancers." (PMID 27793039, 2016). "Furthermore, the aberrant cytoplasmic localization and protein stability of Sirt1 were elucidated to be regulated by PI3K/IGF-1R signaling in human cancer cells." (PMID 27171144, 2016). "However, the colonization was facilitated in the conditioned media from SIRT1-overexpressing fibroblasts, which was commonly shown in three different cancer cell lines." (PMID 26992208, 2016). "Our data demonstrates the elevated expression levels of SIRT1 in all the cancer cell lines studied with plausibility that lower levels of miR-212 in PCa may result in higher levels of SIRT1." (PMID 26439987, 2015). "Therole of SIRT1 in cancer is not fully understood and remains controversial." (PMID 25791281, 2015). "Moreover, the expression of both DBC1 and SIRT1 were correlated with advanced clinicopathological characteristics and poor prognosis of human malignant tumors." (PMID 25823848, 2015).
cancer (continued). "Together, these data provided the first evidence showing that chemotherapies induce SOD1 acetylation and impair its enzymatic activity in cancer cells, which may result from disrupted interaction with SIRT1." (PMID 26008972, 2015). "Our results evoke hope that a strategy for cancer treatment may be developed based on SIRT1 inhibitors." (PMID 26091232, 2015). "Both SIRT1 and Wnt signaling have been shown to attenuate adipogenesis, however, only recently was SIRT1/2 shown to regulate Wnt signaling at multiple levels within a cancer context." (PMID 25569080, 2015). "The ability of dietary MSC to modulate circadian rhythm by enhancing SIRT1 activity may have therefore significant implication in chemoprevention of cancer and other aging-related chronic diseases." (PMID 26544624, 2015). "Notably, patients with a high SIRT1 level exhibited poor cancer-specific survival (GSE17536 CRC data sets, P = 0.016; HR = 1.863, 95% CI of ratio = 1.12 − 3.09; n = 177)." (PMID 26363315, 2015). "Additionally, mammalian SIRT1 is a key regulator of cancer cell survival in the face of cellular stresses." (PMID 25884180, 2015). "The role of SIRT1 in cancer has long been studied and debated." (PMID 25826085, 2015). "Furthermore, SUMOylation by PIASy can modify Sp1 and suppress the expression of the sirtuin 1 (SIRT1) gene in ovarian and lung cancer cells." (PMID 26703734, 2015). "In the present study, we showed that resistance to Hsp90 inhibitors of MDR human cancer cells could be overcome with SIRT1 inhibition." (PMID 26416354, 2015). "SIRT1 plays a dual role in cancer development and progression." (PMID 26318035, 2015). "Moreover, the effects of the expression of DBC1 and SIRT1 in human malignant tumors varied according to cell type." (PMID 25823848, 2015). "Treatment of carcinoma cells with curcumin markedly increased the SIRT1 expression." (PMID 26299580, 2015). "On the other hand, immunohistochemical analysis of a tissue microarray demonstrated that 23 of 82 carcinomas showed lower SIRT1 expression, and 18 of 82 showed higher expression relative to normal colonic mucosa, indicating the complexity of SIRT1 in tumorigenesis." (PMID 25569080, 2015). "These SIRT1 inhibitors can induce selective cytotoxicity in cancer cells in vitro." (PMID 25189993, 2014). "The mammalian ortholog SIRT1 has emerged as an important regulator of cancer and ageing." (PMID 24742694, 2014). "Depending upon the specific genetic background of the cancer cell, SIRT1 inhibition by JQ-101 may utilize different downstream targets of SIRT1 to induce either apoptosis or cell senescence, to suppress cancer cell growth and survival." (PMID 25189993, 2014). "Therefore, when cancer cells are suited to the surrounding environment through Sirt1 regulation, the molecular HIF1 level will decrease, resulting in a negative correlation between Sirt1 and HIF1 expression." (PMID 24959282, 2014). "SIRT1, a member of the class III histone deacetylase family, has been implicated in a range of physiological and pathological processes including aging, metabolism, cancer and inflammation." (PMID 25136908, 2014).
cancer (continued). "Additionally, resveratrol, an activator or Sirt1, has been demonstrated to be effective as a therapy for some cancers." (PMID 24797518, 2014). "Similarly, the epithelial to mesenchymal transition (EMT) is a classic hallmark of tumor metastasis, which has been shown to be induced by SIRT1 activity in certain cancers." (PMID 24897117, 2014). "SIRT1 inhibitors and SIRT1 activators can contribute anti-tumor effects by promoting apoptosis and inhibiting cell growth in cancer with aberrant overexpression of SIRT1, although the precise mechanisms underlying these contradictory activities are not well elucidated." (PMID 25486244, 2014). "Whereas the preponderance of the evidence suggests that SIRT1 in many contexts promotes cancer metabolism by working in conjunction with HIF and MYC family proteins, SIRT3, SIRT4 and SIRT6 all inhibit distinct aspects of the metabolic alterations observed in tumor cells." (PMID 25085992, 2014). "Collectively, these results suggest an important role for SIRT1 in cancer growth and progression." (PMID 25189993, 2014). "SIRT1 protein, which plays an important role in deacetylation, has been demonstrated to be involved in tumorigenesis and lymph node metastasis in various types of human cancers." (PMID 25922660, 2014). "In summary, we have identified JQ-101 as a new SIRT1 inhibitor which may have potential application in cancer treatment through its ability to induce tumor cell apoptosis and senescence and suppress cancer cell invasion." (PMID 25189993, 2014). "SIRT1 has attracted much attention for its functional roles in cancer." (PMID 25189993, 2014). "SIRT1 upregulation has been reported in various malignant tumors in humans and animals." (PMID 25146318, 2014). "Interestingly, SIRT1 is considered as an oncogene that supports the survival of CSCs in various cancers." (PMID 25216517, 2014). "Based on cell-culture models, many studies have shown that SIRT1 can inhibit apoptosis and senescence, suggesting that SIRT1 inhibition may be beneficial for treating certain types of cancers." (PMID 25486244, 2014). "In addition, it has been reported that the FOXO1, FOXO3 and FOXO4 members of the Forkhead transcription factor family interact with Sirt1, leading to increased resistance to stress and apoptosis, and thus to cancer cell survival." (PMID 24959282, 2014). "Recent studies have shown that SIRT1 plays an important role in cancer cell migration and invasion." (PMID 25189993, 2014). "Moreover, Overexpression of SIRT1 has been shown to maintain CSC characteristics in different cancers." (PMID 25216517, 2014). "In cancer cells, SIRT1 has been detected in the promoter of densely hypermethylated tumor suppressor genes (TSGs; e.g., E-cadherin, MLH1, and p27) and may contribute to their transcriptional inactivity." (PMID 25146318, 2014). "Moreover, the high expression rate of SIRT1 was significantly lower in cancer than normal tissues (p = 0.000)." (PMID 25420528, 2014). "This suggests that SIRT1 is important in control of growth in these cancer cells." (PMID 25189993, 2014). "We used a floor-of-the mouth murine model in SCID mice to determine whether SIRT1 inhibits cancer cell metastasis in vivo." (PMID 25424420, 2014). "The effect of JQ-101 on cancer cell growth is greatly attenuated in the SIRT1-silenced cells." (PMID 25189993, 2014).